XAF1 (XIAP associated factor 1)
Diseases named in the same sentence as XAF1 in open-access papers (continued):
Sharing a sentence is not in itself a finding about the gene and the disease.
tumor (continued). "Intriguingly, TRIM28 destabilizes XAF1 through K48-linked polyubiquitination and proteasomal degradation to protect tumor cells from apoptotic stress, indicating its role as an intrinsic antagonist against XAF1 and the antagonistic interplay of XAF1 and TRIM28." (PMID 39532800, 2024). "Therefore, our study uncovers a novel mechanism underlying XAF1-mediated tumor suppression and the XAF1-TRIM28 mutual antagonism." (PMID 39532800, 2024). "XAF1 expression level is tightly linked to tumor development and increasing XAF1 may be imperative in delaying the growth of cancer cells." (PMID 27097110, 2016). "Loss of XAF1 expression is correlated strongly with tumor staging and progression in human cancers." (PMID 24980821, 2014). "Indeed, we found low XAF1 protein expression in ccRCC to be associated with progression of tumour stage and grade." (PMID 19664236, 2009). "Likewise, deficiency of XAF1 expression is strongly associated with tumor progression." (PMID 23685456, 2013). "In the present study, we found that XAF1 destabilizes TRIM28 to suppress tumor cell malignancy whereas TRIM28 destabilizes XAF1 to protect tumor cells from apoptotic stresses." (PMID 39532800, 2024). "Although a growing body of evidence indicates that tumor suppression function of XAF1 stems mainly from its activity to control ubiquitin E3 ligases, only a few XAF1-binding E3 ligases have been identified." (PMID 39532800, 2024). "XAF1 exerts apoptosis-promoting effect more strongly in TRIM28+/+ versus XAF1−/− tumor cells and suppresses tumor cell growth, migration, invasion, and epithelial-to-mesenchymal transition and xenograft tumor growth in a highly TRIM28-dependent fashion." (PMID 39532800, 2024). "XAF1 expression is inversely correlated with TRIM28 expression in cancer cell lines and tumor tissues and more tightly associated with the survival of TRIM28-high versus TRIM28-low patients." (PMID 39532800, 2024). "Our study also provides evidence that TRIM28 elevation due to XAF1 inactivation protects tumor cells from apoptotic stresses." (PMID 39532800, 2024). "TUNEL and cl-PARP immunoblot assays of tumor tissues showed that apoptosis-inducing effect of XAF1 is substantially lower in TRIM28−/− tumors compared to TRIM28+/+ tumors, supporting the TRIM28-dependency of its growth inhibition function." (PMID 39532800, 2024). "Together, these support that XAF1 suppresses tumor cell malignancy at least in part by targeting TRIM28." (PMID 39532800, 2024). "Together, this study uncovers a novel mechanism by which XAF1 suppresses tumor malignancy and an important role for XAF1-TRIM28 interplay in governing stress response, illuminating the mechanistic consequence of its alteration during tumorigenic process." (PMID 39532800, 2024). "Collectively, we found that XAF1 destabilizes TRIM28 and thereby antagonizes its oncogenic activity to suppress tumor cell malignancy while TRIM28 destabilizes XAF1 to protect tumor cells from apoptotic stresses." (PMID 39532800, 2024). "XAF1 is a tumor suppressor gene known to trigger apoptosis by counteracting the inhibitory effect of the IAP protein family that in turn inhibit caspases." (PMID 36749641, 2023). "Collectively, our study identifies XAF1 as a key regulator of ER stress response, illuminating its novel role as a tumor suppressor and the mechanistic consequence of its epigenetic alteration in tumorigenesis." (PMID 35902580, 2022). "X-linked inhibitor of apoptosis (XIAP)-associated factor 1 (XAF1) is identified as an ISG (14, –, 16), which mainly mediates the IFN-β-TRAIL-induced apoptosis in multiple cell lines and functions as a tumor suppressor (14, 17, –, 19)." (PMID 35972291, 2022). "Several of these highly expressed genes have growth inhibitory and/or tumor suppressor functions (e.g. XAF1, SP100)." (PMID 34997070, 2022). "To investigate the XAF1 role in tumor response to TG in vivo, we carried out mouse tumor xenograft assays using XAF1+/+ and XAF1−/− sublines of LoVo cells." (PMID 35902580, 2022).
tumor (continued). "Immunohistochemistry (IHC) study of 70 human breast tissues also identified a frequent reduction of XAF1 in tumor versus normal tissues and its inverse correlation with GRP78 expression." (PMID 35902580, 2022). "A series of assays using transient knockdown and overexpression or tetracycline-inducible XAF1 (Tet-XAF1) system confirmed that XAF1 increases tumor cell sensitivity to ER stress-mediated apoptosis." (PMID 35902580, 2022). "In tumor xenograft assays, XAF1−/− tumors display substantially lower regression compared to XAF1+/+ tumors in response to cytotoxic dose of ER stress inducer." (PMID 35902580, 2022). "IFN regulatory factor-1 (IRF-1), XIAP-associated factor 1 (XAF1), and cGMP-dependent protein kinase (PKG) II, as tumor suppressor genes, also can inhibit proliferation and promote apoptosis of GC in a similar way." (PMID 36505792, 2022). "This is supported by the finding that blockade of XAF1 induction disrupts tumor regression by treatment of ER stress inducer in vivo." (PMID 35902580, 2022). "It has been shown that XAF1 is expressed in normal cells and tissues but present at very low or undetectable levels in tumor cell lines and tissues as a tumor suppressor." (PMID 33747900, 2021). "X-linked apoptosis protein-related factor 1 (XAF1), whose expression is also induced by the interferon (IFN) signal, is also a tumor suppressor." (PMID 34206713, 2021). "Another IFN‐regulated gene is XAF1 (X‐linked inhibitor of apoptosis [XIAP]‐associated factor 1), a tumor suppressor initially identified as XIAP inhibitor." (PMID 33734579, 2021). "XAF-1 is a pro-apoptotic tumor suppressor that can bind to and disrupt the anti-caspase activity of XIAP via sequestering XIAP31,33." (PMID 33130818, 2020). "It appears XAF1 through unclear mechanisms promotes adaptive resistance and aggressive tumor phenotype in GBM when challenged with TMZ." (PMID 31575897, 2019). "XAF1 is a tumor suppressor, which induces apoptosis and inhibits tumor growth in gastric cancer and HCC." (PMID 31861751, 2019). "These support that XAF1 inhibits NF-κB tumor-promoting function by reinforcing IRF-1 interaction with a subset of coregulated target promoters." (PMID 30042418, 2018). "Expression levels of IRF-1 and XAF1 correlate tightly in both cancer cell lines and primary tumors, and XAF1-induced tumor regression is markedly attenuated in IRF-1-depleted tumors." (PMID 30042418, 2018). "Together, this study adds a new tumor suppression mechanism by which XAF1 functions as a coactivator of stress-inducible transcription factors, such as IRF-1." (PMID 30042418, 2018). "As for MAT2B, it has been demonstrated to inhibit cell growth, colony formation and induction of apoptosis of A375 and mel-rm cell lines in vitro, affect the expression of BCL2 and XAF1 proteins, and prolong the growth of transplanted tumor in vivo." (PMID 30379973, 2018). "To delineate the possible implication of the IRF-1−XAF1 axis alteration in tumorigenesis, we characterized expression status of IRF-1 and XAF1 in established cell lines and primary tumor tissues." (PMID 30042418, 2018). "In the present study, we identified that XAF1 attenuates NF-κB-mediated transcription of tumor-promoting genes by facilitating IRF-1 repression of p65/RelA-mediated transcription." (PMID 30042418, 2018).
tumor (continued). "Collectively, this study identifies a novel mechanism of XAF1-mediated tumor suppression, uncovering XAF1 as a feedback coactivator of IRF-1 under stressful conditions." (PMID 30042418, 2018). "IB assay of tumor tissues revealed that XAF1 induction leads to MMP9 reduction and strongly increases both cleaved PARP and CASP3 levels in sh-Control but not sh-IRF-1 tumors." (PMID 30042418, 2018). "To investigate the functional interplay of IRF-1 and XAF1 in tumor suppression, we initially characterized their interrelationship in stress-induced apoptosis." (PMID 30042418, 2018). "Meanwhile, XAF1 inhibits NF-κB-mediated tumor cell malignancy by reinforcing IRF-1 binding to a subset of coregulated promoters." (PMID 30042418, 2018). "In vitro studies showed that XAF1 suppresses tumor cell growth and enhances the cellular response to various apoptotic stimuli." (PMID 28122345, 2017). "These in vitro data are in accordance with other reports, demonstrating that enhanced XAF1 expression induces apoptosis in tumor cells and in xenografts." (PMID 28122345, 2017). "Control and XAF1-overexpressing SK-N-SH cells were subcutaneously engrafted into the left and right flanks of the mice respectively and tumor growth was monitored over a period of 33 days." (PMID 27097110, 2016). "Gene expression profiling of mammary glands revealed significantly elevated levels of Xaf1, an apoptotic inducer and tumor-suppressor gene, in knockout mice." (PMID 27124579, 2016). "To test the potential significance of XAF1 expression on tumor growth in vivo, we investigated the effects of XAF1 on tumor growth using mouse xenograft models." (PMID 27097110, 2016). "Restoration of XAF1 expression was found to induce apoptosis and inhibit tumor growth in these cancers, implicating XAF1 as a candidate tumor suppressor." (PMID 27097110, 2016). "A comparable and modest tumor growth was initially observed in the XAF1 knockdown and control groups over a period of 46 days." (PMID 27097110, 2016). "XAF1 is a pro-apoptotic protein that also targets XIAP and can enhance tumor cell susceptibility to cisplatin and radiotherapy." (PMID 27613060, 2016). "With INF-γ treatment, we confirmed that BRD7 regulates the tumor suppression activity of XAF1 in vivo." (PMID 26802028, 2016). "XAF1 is a tumor suppressor that is frequently silenced in many human cancers, but it can inhibit cell proliferation and induce apoptosis in some cancer types." (PMID 26802028, 2016). "Using mice xenografts, we showed that XAF1 knockdown increases tumor growth whereas XAF1 overexpression decreases tumor progression." (PMID 27097110, 2016). "In contrast to the effect of XAF1 knockdown, overexpression of XAF1 led to a decrease in tumor growth rate." (PMID 27097110, 2016). "In this study, we investigated the effects of adenovirusmediated XAF1 expression on liver tumor growth and tumor angiogenesis." (PMID 24980821, 2014). "X-linked inhibitor of apoptosis (XIAP)-associated factor 1 (XAF1), a XIAP-binding protein, is a tumor suppressor gene." (PMID 24980821, 2014). "Our results demonstrate that XAF1 inhibits tumor growth by inducing apoptosis and inhibiting tumor angiogenesis." (PMID 24980821, 2014). "IHC showed that XAF1 expression was located in both cytoplasm and nuclei, and its expression was markedly increased in tumor tissues treated with Ad5/F35-XAF1 compared to that with Ad5/F35-Ctrl." (PMID 24980821, 2014). "In summary, our study demonstrates that the restoration of XAF1 expression induces tumor cell apoptosis and inhibits tumor angiogenesis." (PMID 24980821, 2014). "In this study, we have shown, for the first time, that the restoration of XAF1 expression inhibited tumor growth and suppressed tumor angiogenesis in HCC both in vitro and in vivo." (PMID 24980821, 2014).
tumor (continued). "In 168 cases that showed XAF1 methylation in tumor tissues, 141 displayed XAF1 methylation in their paired serum, giving a consistency of 83.9% between them." (PMID 23826230, 2013). "Overexpression of XAF1 enhances chemosensitivity and cell death, and inhibits tumor growth in various cancers including gastric, colon, pancreatic and prostate cancers." (PMID 23685456, 2013). "Another member of Bcl-2 family upregulated in HT-29R cell line, XIAP associated factor 1 (XAF1), has an important role in modulation of apoptosis in tumor cells by inhibiting the caspase-3 activity." (PMID 23865481, 2013). "X-linked inhibitor of apoptosis (XIAP)-associated factor 1 (XAF1) is a novel negative regulator of XIAP, which reverses XIAP’s protection role on tumor cells." (PMID 23826230, 2013). "Next, we confirmed the consistency in XAF1 methylation between tumor tissues and corresponding serum." (PMID 23826230, 2013). "This is the first study to demonstrate that low XAF1 protein expression is related to tumour progression in patients with ccRCCs." (PMID 19664236, 2009). "This study assessed the expression of XAF1 protein in tumour tissue obtained from 291 ccRCC patients and 68 normal renal tissue samples, utilizing immunohistochemistry on a tissue-micro-array." (PMID 19664236, 2009). "In conclusion, low XAF1 protein levels in ccRCCs were related to poor tumour differentiation, advanced tumour stages and unfavourable outcome." (PMID 19664236, 2009). "These recent findings identify XAF1 as a candidate tumor suppressor at the junction of several major pathways leading to apoptosis." (PMID 17376236, 2007). "XAF1, a regulator of apoptosis, promotes tumor cell survival when suppressed." (PMID 41304780, 2025). "Considering that XAF1 has multiple ZF domains (ZF1-ZF7), our data strongly support that XAF1 may act as a bridge or adaptor molecule to control the stability of multiple tumor-associated ubiquitin E3 ligases." (PMID 39532800, 2024). "Therefore, our study adds XAF1 to TRIM28’s targets of tumor suppression function and identifies a novel mechanism for TRIM28-driven tumor progression." (PMID 39532800, 2024). "Therefore, our study establishes XAF1 as an intrinsic antagonist of TRIM28, illuminating a novel mechanism underlying its tumor suppression function." (PMID 39532800, 2024). "Given that XAF1 is a stress-inducible growth inhibitor, it is likely that stress-induced high XAF1 could activate its tumor suppression signaling through TRIM28 destruction more efficiently in TRIM28-high versus TRIM28-low tumors." (PMID 39532800, 2024). "In addition to apoptosis-promoting role, XAF1 is involved in various cellular aspects, including autophagy, G2/M cell cycle checkpoint, and tumor angiogenesis." (PMID 39532800, 2024). "XAF1 effect on TRIM28 level was also observed in various types of tumor cell lines." (PMID 39532800, 2024). "Thus, XAF1 has been recognized as a tumor suppressor, and its expression is generally downregulated in several cancer cells." (PMID 37189754, 2023). "Numerous studies have reported that XAF1 dysfunction plays a vital role in tumor progression." (PMID 35625619, 2022). "XAF1 plays a role as an apoptosis-promoting tumor suppressor." (PMID 35829914, 2022). "XAF1 also regulates autophagy, tumor angiogenesis, and G2/M checkpoint of the cell cycle." (PMID 35902580, 2022). "To further confirm the role of XAF1 in Fdcyd treatment on tumor cells, we assessed whether re-expression of XAF1 could alleviate apoptosis, DNA damage and cell cycle arrest." (PMID 35719970, 2022). "Considering that Nrf2 and XAF1 are up- and downregulated, respectively in many human cancers, alteration of the Nrf2-XAF1 axes might contribute to tumor resistance to ER stress." (PMID 35902580, 2022).
tumor (continued). "Our study uncovers a novel tumor suppressive role of XAF1, raising the possibility that the restoration of the XAF1-GRP78 and/or XAF1-CHIP-IRE1α interplay could be an attractive avenue for the therapeutic intervention of tumor progression." (PMID 35902580, 2022). "Given that tumor cells with XAF1 hypermethylation require high dose of stress inducers for XAF1 activation, promoter methylation status of XAF1 could be a predictive marker for the clinical efficacy of ER stress-based therapy." (PMID 35902580, 2022). "The most interesting observations related to the paradoxical function of XAF1, a previously reported tumor suppressor gene whose expression could induce apoptosis in tumor cells." (PMID 31575897, 2019). "In addition to VGLL4, the other IAP-binding protein, X-linked inhibitor of apoptosis (XIAP)-associated factor 1 (XAF-1), is also regarded as a tumor suppressor." (PMID 31781493, 2019). "This suggested that XAF1 may have an aggressive and tumor-promoting role in GBM that was novel and paradoxical to its tumor suppressor role in other cancers." (PMID 31575897, 2019). "On this basis, we assessed whether XAF1 inhibits tumor cell migration and invasion by blocking p65/RelA-mediated MMP9 transcription through IRF-1 induction." (PMID 30042418, 2018). "Furthermore, XAF1 inhibits growth, migration, and invasion of tumor cells and suppresses in vivo tumor growth in a highly IRF-1-dependent manner, indicating that the tumor suppressive role of XAF1 is tightly linked to its ability to bind and activate IRF-1." (PMID 30042418, 2018). "The MS-HRM-facilitated detection of the XAF1 methylation, presented in this study, thus could provide a fast and cheap diagnostic tool for assessing the IDH status in tumor samples." (PMID 28122345, 2017). "XAF1 protein expression was shown to suppress tumor cell growth and enhance cellular response to various apoptotic stimuli, such as 5-fluorouracil, etoposide, H2O2, γ-irradiation, UV light and TNFα, whereas knockdown of its expression protected cells from the stressors." (PMID 28122345, 2017). "Due to the tumor-suppressing nature of XAF1, we anticipated a similar impact in HGG." (PMID 28122345, 2017). "Considering XAF1 as tumor suppressor, the link between XAF1-M and an improved OS/PFS might be attributed to the overall G-CIMP effects, which themselves are associated with a better prognosis." (PMID 28122345, 2017). "As epigenetic silencing of XAF1 occurs in different tumor entities, we further addressed the question whether the XAF1 promoter methylation is associated with clinical outcomes in HGG patients." (PMID 28122345, 2017). "Thus, an extended screening of primary GB with frequently occurring IDHwt genotype as to the promoter methylation state of XAF1 is necessary to provide valuable information about XAF1 methylation as an independent biomarker for this tumor entity." (PMID 28122345, 2017). "Although XAF1 serves as a tumor-suppressor gene, the role of XAF1 in cellular senescence remains unclear." (PMID 26802028, 2016). "While XAF1 expression in tumor cells is generally very low, quantities of alternatively spliced truncated isoforms lacking the XIAP interaction have been found to increase in some aggressive cancers and have been suggested as potential biomarkers of disease status." (PMID 27613060, 2016). "This suggests that XAF1 may be a potential tumor suppressor and prognostic marker whereby its low expression down-regulates an important apoptotic mechanism for tumor suppression." (PMID 27097110, 2016). "XAF1 (XIAP-associated factor 1) is a novel XIAP binding protein which could disturb the combining of XIAP with caspases, abolishes its protection on tumor cells and results in tumor cell apoptosis." (PMID 23826230, 2013). "More interestingly, transition from negative to positive of circulating XAF1 methylation after surgery was significantly associated with tumor recurrence." (PMID 23826230, 2013).